ALS2CL (ALS2 C-terminal like)
Description:
Acts as a guanine nucleotide exchange factor (GEF) for Rab5 GTPase. Regulates the ALS2-mediated endosome dynamics.
Synonyms: FLJ36525; RN49018; DKFZp686I0110
Tractability: PROTAC: ubiquitination databases record sites on it.
Gene: Protein-coding gene on chromosome 3 (46,668,994 to 46,694,071, reverse strand). Ensembl gene ENSG00000178038.
Subcellular location: Cytoplasm
Pathways (Reactome):
Vesicle-mediated transport: RAB GEFs exchange GTP for GDP on RABs
Gene Ontology:
Molecular function: protein binding; guanyl-nucleotide exchange factor activity; small GTPase binding
Biological process: endosomal transport
Cellular component: cytoplasm; cytoplasmic vesicle; cytosol
Genetic constraint (gnomAD): Loss-of-function variants: 117 observed, 126.35 expected, observed/expected ratio (o/e) 0.93, 90% interval 0.8 to 1.08. The upper end of that interval is the gene's LOEUF score, 1.08, which puts it in group 4 of 6, group 1 being the genes least tolerant of losing a copy. Missense variants: 1,174 observed, 1,238.6 expected, observed/expected ratio (o/e) 0.95, 90% interval 0.9 to 1. Synonymous variants: 519 observed, 521.8 expected, observed/expected ratio (o/e) 0.99, 90% interval 0.93 to 1.07.
Homologues: Orthologues: chimpanzee ALS2CL (99% identical), macaque ALS2CL (97% identical), dog ALS2CL (86% identical), pig ALS2CL (84% identical), rat Als2cl (82% identical), rabbit ALS2CL (81% identical), mouse Als2cl (81% identical), guinea pig ALS2CL (77% identical), tropical clawed frog als2cl (48% identical), Drosophila melanogaster CG14490 (5% identical). Paralogues in human: RSPH10B (14% identical), RSPH10B2 (14% identical), MORN1 (10% identical), RSPH1 (7% identical), MORN3 (6% identical), SETD7 (6% identical), MORN2 (3% identical).
Diseases named in the same sentence as ALS2CL in open-access papers:
ALS2CL is named in the same sentence as 9 diseases in open-access papers, as found by Europe PMC text mining. Sharing a sentence is not in itself a finding about the gene and the disease. The quoted sentences say what the papers report.
leukemia (1 paper, 2013). A malignant (clonal) hematologic disorder, involving hematopoietic stem cells and characterized by the presence of primitive or atypical myeloid or lymphoid cells in the bone marrow and the blood. "Some were already associated with T-CD8+ leukemias (Il2ra; and Pdgfrb) and others were associated with other types of T-leukemias or cancer (Irf4, Hrb, Depdc6, Als2cl, Tle4 and Cdc42ep3), thus validating our approach." (PMID 23902727, 2013).
osteoporosis (1 paper, 2024). A condition of reduced bone mass, with decreased cortical thickness and a decrease in the number and size of the trabeculae of cancellous bone (but normal chemical composition), resulting in increased fracture incidence. "Our study systematically identified seven candidate hub genes (PDP1, ALS2CL, VLDLR, PLEKHA6, PPP1CB, MOSPD2, and METTL9) through a combination of various bioinformatics analyses and machine learning algorithms, and provided a nomogram for diagnosing sarcopenia associated with osteoporosis." (PMID 38831425, 2024). "We identified 7 candidate hub genes (PDP1, ALS2CL, VLDLR, PLEKHA6, PPP1CB, MOSPD2, METTL9) and constructed column line plots for osteoporosis combined with sarcopenia." (PMID 38831425, 2024). "A notable finding is the identification of 7 key candidate genes (PDP1, ALS2CL, VLDLR, PLEKHA6, PPP1CB, MOSPD2, and METTL9), and the development of a nomogram for diagnosing osteoporosis in sarcopenia patients." (PMID 38831425, 2024).
tumours (1 paper, 2023). "Alternative splicing events in ALS2CL are upregulated in primary tumours compared to normal tissues and may be prognostic markers for overall survival and disease-free survival (DFS)." (PMID 37924098, 2023).
ALS2CL also shares sentences with these, for which no sentence is quoted: cancer (1 paper); head and neck squamous cell carcinoma (1); hepatocellular carcinoma (1); peripheral T-cell lymphomas (1); sarcopenia (1); schizophrenia (1).